SKA2 (spindle and kinetochore associated complex subunit 2)
Diseases named in the same sentence as SKA2 in open-access papers (continued):
Sharing a sentence is not in itself a finding about the gene and the disease.
lymph node metastasis (2 papers, 2021). "One of the studies reported that the overexpression of SKA2 was significantly associated with the clinical stage and lymph node metastasis." (PMID 35095717, 2021).
Alzheimer disease (1 paper, 2024). A progressive, neurodegenerative disease characterized by loss of function and death of nerve cells in several areas of the brain leading to loss of cognitive function such as memory and language. "Overall, our findings suggest that SKA2-regulated, hyperactive SA facilitates neuroinflammation and is linked to Alzheimer’s disease, providing mechanistic insight into the biology of neuroinflammation." (PMID 38528004, 2024).
Anxiety (1 paper, 2015). Intense feelings of nervousness, tension, or panic often arise in response to interpersonal stresses. "Instead, it is likely that the underlying factor resulting in significant interactions with SKA2 is differential HPA axis sensitivity, which is an underlying feature of both anxiety and trauma." (PMID 26305478, 2015).
Atrophy (1 paper, 2024). Any weakening or degeneration, especially through lack of use. "Hippocampal Ska2 knockdown in male mice hyperactivates SA resulting in neuroinflammation, subsequent neurodegeneration and complete hippocampal atrophy within six weeks." (PMID 38528004, 2024). "The severe hippocampal atrophy observed at 4 weeks following Ska2 KD resulted in expected spatial memory (Y-maze) and novel object recognition memory impairments in mice." (PMID 38528004, 2024). "Ska2 KD resulted in complete hippocampal atrophy within 6 weeks of the viral injection." (PMID 38528004, 2024).
Cognitive impairment (1 paper, 2024). Abnormal cognition is characterized by deficits in thinking, reasoning, or remembering. "Excessive SA in mice, which was induced via KD of Ska2, resulted not only in severe hippocampal neuroinflammation and neurodegeneration, but also in cognitive impairment." (PMID 38528004, 2024).
hippocampal atrophy (1 paper, 2024). "Overactivation of this pathway in mice through viral-mediated KD of hippocampal Ska2 resulted in strong microglial activation and recruitment, leading to complete hippocampal atrophy within 6 weeks of viral injection." (PMID 38528004, 2024).
kidney cancer (1 paper, 2021). Primary or metastatic malignant neoplasm involving the kidney. "In addition, the mRNA levels of SKA1, SKA2, and SKA3 were significantly overexpressed in several other tumors, including breast, lung, colorectal, and kidney cancer." (PMID 35095717, 2021).
mood disorder (1 paper, 2024). A cognitive disorder a disturbance in which the person's mood is hypothesized to be the main underlying feature. "SKA2 methylation patterns have been linked to stress response dysregulation and mood disorder pathophysiology." (PMID 38792892, 2024). "Specifically, genes, such as NR3C1, SLC6A4, BDNF, FKBP5, SKA2, and OXTR, exhibit alterations in DNA methylation patterns that are frequently linked to mood disorders." (PMID 38792892, 2024).
prostate adenocarcinoma (1 paper, 2022). "Except for kidney renal clear cell carcinoma, KIRP, and prostate adenocarcinoma, we observed that tumor tissues exhibited significantly high expression of SKA2 compared to that of normal tissues." (PMID 36439516, 2022).
psychosis (1 paper, 2019). "Our analysis also highlights genes identified via GWAS studies and implicated in psychosis (ZNF804A) and suicidal behavior (SKA2)." (PMID 31481758, 2019).
renal cell carcinoma (1 paper, 2016). "In this study, we evaluate in vitro and in vivo the functional relationship between CREB and SKA2 in renal cell carcinoma (RCC)." (PMID 26824422, 2016). "The present study indicated that CREB functions as tumor oncogene, promoting renal cell cancer proliferation, probably by upgrading SKA2 expression." (PMID 26824422, 2016).
stress-related disorder (1 paper, 2020). Stress-related disorders are mental health disorders that are a result of an atypical response to both short and long-term anxiety due to physical, mental, or emotional stress. "Moreover, SPRY4-IT1, a long non-coding RNA derived from the second intron of SPRY4, has been shown to interact with SKA2, a gene that was suggested to be a promising biomarker for suicidal behavior, stress susceptibility, and stress-related disorders such as PTSD." (PMID 31931860, 2020).
substance abuse (1 paper, 2016). The use of a drug for a reason other than which it was intended or in a manner or in quantities other than directed. "Along with substance abuse, trauma exposure has recently been shown to influence SKA2 methylation." (PMID 27822318, 2016).
viral infection (1 paper, 2024). "Remarkably, KD of Ska2 induced pronounced neurodegeneration compared to viral infection with a scrambled control shRNA." (PMID 38528004, 2024).
tumor (18 papers, 2007 to 2024). "Spindle and kinetochore‐associated protein 2 (SKA2) was identified as a tumor promoter and participated in various critical cellular mechanisms, including cell growth, metastasis, cell cycle, and so on." (PMID 33244865, 2021). "Taken together, aberrant expression of SKA2 is associated with tumor progression." (PMID 36860919, 2023). "Therefore, target genes regulated by SKA2 are needed to be explored for understanding the underlying mechanism of SKA2 promoting tumor progression." (PMID 36860919, 2023). "Spindle and kinetochore-associated protein 2 (SKA2) is a cell cycle regulatory protein that is upregulated in a variety of malignant tumors and is considered a tumor promoter." (PMID 37204526, 2023). "Subsequent experimentation revealed that SKA2, a candidate tumor-promoter, probably promotes BC cell proliferation and migration via upregulating SKA2 expression." (PMID 34845974, 2021). "The present study indicated that SKA2, which significantly correlated with the tumor stage, is highly expressed in BC." (PMID 34845974, 2021). "It comprises three proteins (Ska1, Ska2, and Ska3) with theorized roles in chromosomal instability and tumor development, and its overexpression has been widely reported in a variety of tumors." (PMID 34045512, 2021). "Consistently, silencing circ_0008039 restrained tumor growth via increasing miR‐140‐3p and decreasing SKA2." (PMID 33244865, 2021). "SKA2 functions as a tumor oncogene, participating in a multiplicity of important cellular mechanisms consisting of cell growth, metastasis, and cell cycle regulation." (PMID 34845974, 2021). "We further uncovered that silencing circ_0008039 restrained tumor growth in vivo through enhancing miR‐140‐3p and decreasing SKA2." (PMID 33244865, 2021). "In RCC tumor samples from patients, mRNA for SKA2 were plotted near those of CREB in each sample, with significantly increased immunohistochemical staining of higher SKA2 and CREB in the higher TNM stages." (PMID 26824422, 2016). "Decreased expression of CREB suppressed RCC cell growth and xenograft tumor formation, accompanied by reduced expression of SKA2." (PMID 26824422, 2016). "Intense signals of CREB and SKA2 were observed in the nucleus of tumor cells in TNM stages III and IV RCC tissues, more than those in stages I and II." (PMID 26824422, 2016). "The in vivo work showing reduction of tumor growth, paralleled with lower SKA2 expression, merits further corroboration with statistically significant data." (PMID 26824422, 2016). "In serial sections of the same patient's tumor, the relative mRNA levels of SKA2 were plotted near that of CREB in each patient, a significant positive correlation was found (p < 0.05; r = 0.871)." (PMID 26824422, 2016). "The results revealed that SKA2 mRNA level was significantly up-regulated in RCC tissues compared to their matched adjacent non-tumor tissues." (PMID 26824422, 2016). "NF-κB binds directly to the SKA2 promoter region to activate the transcription of SKA2 and miR-301a and also enhances persistent NF-κB activation to facilitate tumor growth, thus suggesting a feedback loop to moderate SKA2 function." (PMID 25115181, 2014). "Next, we detected the levels of circ_0008039, miR‐140‐3p, and SKA2 in tumor samples." (PMID 33244865, 2021). "From these data, we demonstrated that interference of circ_0008039 could significantly suppress xenograft tumor growth through increasing miR‐140‐3p and decreasing SKA2." (PMID 33244865, 2021). "Additionally, suppression of circ_0008039 obviously decreased the protein expression of SKA2 in tumor tissues." (PMID 33244865, 2021). "Similarly, SKA2 expression level was significantly increased in tumor tissues compared with normal tissues (P<0.05)." (PMID 32565988, 2020). "In vivo experiments also confirmed that miR-141 inhibited xenograft tumor growth by targeting SKA2." (PMID 27121316, 2016). "The SKA2 levels in these tumors were reduced in line with reduced tumor growth." (PMID 26824422, 2016).
tumor (continued). "Western blot analyses showed that SKA2 expression was decreased in the LV-miR-141 and sh-HOTAIR xenograft tumor." (PMID 27121316, 2016). "To determine whether SKA2 was regulated by the effect of CREB in vivo, we tested SKA2 protein and mRNA levels in tumor tissues isolated from the mice which injected with OS-RC-2 cells containing shCREB or scramble." (PMID 26824422, 2016). "Additionally, SKA2 expression exhibited a significantly positive association with the CD8 + T cells, macrophages, neutrophils infiltration, and tumor purity, and a negative association with CD4 + T and Dendritic cells infiltration (P < 0.05)." (PMID 34845974, 2021). "At the same time, SKA2 may take part in NT21MP, which regulates tumor biological activity." (PMID 30104400, 2018).
cancer (9 papers, 2017 to 2023). A tumor composed of atypical neoplastic, often pleomorphic cells that invade other tissues. "Previous studies have demonstrated that SKA2 co-localized with GR in cell nuclei, and regulated cancer cell proliferation." (PMID 36860919, 2023). "It had been reported that dysregulation of SKA2 was strongly related to progression of various cancers." (PMID 33244865, 2021). "Recent studies reported that the gene pair of PRR11 and SKA2 is involved in tumorigenesis and cancer progression." (PMID 32565988, 2020). "SKA2, a novel cell cycle gene, has been proposed as a biomarker and therapeutic target against cancer." (PMID 33224872, 2020). "Nevertheless, downstream genes regulated by SKA2 in cancer cells are still vacant." (PMID 36860919, 2023). "SKA2 was also found to promote proliferation and invasion of cancer cells." (PMID 35095717, 2021). "Previous study has shown that SKA2 co-localizes and interacts with glucocorticoid receptor (GR), and enhancing the cancer cell proliferative response to IGF-1 exposure 8, suggesting that SKA2 should be capable of regulating its target genes to augment cancer cell progression." (PMID 36860919, 2023).
neurodegenerative disease (1 paper, 2024). A disorder of the central nervous system characterized by gradual and progressive loss of neural tissue and neurologic function. "It is worth mentioning that while we have focused on AD as an illustrative example, it may be plausible that SKA2, FKBP5, and the SA pathway may also play roles in other neurodegenerative diseases." (PMID 38528004, 2024).
SKA2 also shares sentences with these, for which no sentence is quoted: ovarian carcinoma (2 papers); brain diseases (1); breast tumours (1); cervical adenocarcinoma (1); cognitive decline (1); lung squamous cell carcinoma (1); non-small cell lung carcinoma (1).